ERAP1 (endoplasmic reticulum aminopeptidase 1)
Description:
Aminopeptidase that plays a central role in peptide trimming, a step required for the generation of most HLA class I-binding peptides. Peptide trimming is essential to customize longer precursor peptides to fit them to the correct length required for presentation on MHC class I molecules. Strongly prefers substrates 9-16 residues long. Rapidly degrades 13-mer to a 9-mer and then stops. Preferentially hydrolyzes the residue Leu and peptides with a hydrophobic C-terminus, while it has weak activity toward peptides with charged C-terminus. May play a role in the inactivation of peptide hormones. May be involved in the regulation of blood pressure through the inactivation of angiotensin II and/or the generation of bradykinin in the kidney.
Synonyms: A-LAP; PILS-AP; APPILS; ARTS1; KIAA0525; ARTS-1; ERAAP1; ALAP; ERAAP; PILSAP
Tractability: Small molecule: a drug acting on it is in phase 2 or 3 trials; a structure with a bound ligand is known; a high-quality ligand is known; it has a high-quality binding pocket. Antibody: its Gene Ontology location is reachable by antibodies, with high confidence; UniProt predicts a signal peptide or a membrane-spanning region; the Human Protein Atlas places it where antibodies can reach. PROTAC: ubiquitination databases record sites on it; its protein half-life has been measured; a small molecule that binds it is known.
Target class: Protease; Enzyme; Metallo protease; Metallo protease MAE clan; Metallo protease M1 family
Gene: Protein-coding gene on chromosome 5 (96,760,810 to 96,808,100, reverse strand). Ensembl gene ENSG00000164307.
Subcellular location: Endoplasmic reticulum membrane
Subcellular location (Human Protein Atlas): Cytosol; Nucleoplasm; Plasma membrane; Predicted to be secreted
Pathways (Reactome):
Immune System: Antigen Presentation: Folding, assembly and peptide loading of class I MHC
Gene Ontology:
Molecular function: aminopeptidase activity; endopeptidase activity; interleukin-6 receptor binding; metalloexopeptidase activity; protein binding; interleukin-1, type II receptor binding; metalloaminopeptidase activity; zinc ion binding; metallopeptidase activity; peptidase activity
Biological process: antigen processing and presentation of peptide antigen via MHC class I; membrane protein ectodomain proteolysis; angiogenesis; antigen processing and presentation of endogenous peptide antigen via MHC class I; fat cell differentiation; peptide catabolic process; proteolysis; regulation of blood pressure; regulation of innate immune response; response to bacterium
Cellular component: endoplasmic reticulum; extracellular exosome; extracellular region; membrane; peptidase complex; cytosol; endoplasmic reticulum lumen; cytoplasm; endoplasmic reticulum membrane
Genetic constraint (gnomAD): Loss-of-function variants: 80 observed, 101.7 expected, observed/expected ratio (o/e) 0.79, 90% interval 0.66 to 0.95. The upper end of that interval is the gene's LOEUF score, 0.95, which puts it in group 4 of 6, group 1 being the genes least tolerant of losing a copy. Missense variants: 989 observed, 1,161.2 expected, observed/expected ratio (o/e) 0.85, 90% interval 0.81 to 0.9. Synonymous variants: 395 observed, 419.07 expected, observed/expected ratio (o/e) 0.94, 90% interval 0.87 to 1.02.
Homologues: Orthologues: chimpanzee ERAP1 (99% identical), macaque ERAP1 (96% identical), pig ERAP1 (87% identical), rabbit ERAP1 (87% identical), guinea pig ERAP1 (86% identical), dog ERAP1 (84% identical), mouse Erap1 (84% identical), rat Erap1 (83% identical), tropical clawed frog erap1 (64% identical), zebrafish erap1b (62% identical), zebrafish erap1a (57% identical), Drosophila melanogaster SP1029 (31% identical), and 13 more. Paralogues in human: ERAP2 (50% identical), LNPEP (45% identical), ANPEP (32% identical), ENPEP (32% identical), NPEPPS (31% identical), LVRN (29% identical), TRHDE (26% identical), RNPEP (13% identical), RNPEPL1 (13% identical), LTA4H (11% identical), AOPEP (11% identical).
Diseases named in the same sentence as ERAP1 in open-access papers:
ERAP1 is named in the same sentence as 108 diseases in open-access papers, as found by Europe PMC text mining. Sharing a sentence is not in itself a finding about the gene and the disease. The quoted sentences say what the papers report.
psoriasis (71 papers, 2011 to 2026). An autoimmune condition characterized by red, well-delineated plaques with silvery scales that are usually on the extensor surfaces and scalp. "Briefly, ERAP1 variants have been extensively studied in the context of autoimmune diseases, such as ankylosing spondylitis (AS) and psoriasis, as well as in cancer susceptibility." (PMID 40226591, 2025). "Key ERAP1 gene polymorphisms involved in mediating the immune response in psoriasis include SNPs: rs26653 (Arg127Pro), rs30187 (Lys528Arg), rs27044 (Gln730Glu), and rs27524." (PMID 38534723, 2024). "ERAP1 polymorphisms have been linked to several autoimmune diseases, including psoriasis, with the risk allele A." (PMID 38898675, 2024). "Further data demonstrate associations of ERAP1 not only with Ankylosing Spondylitis but also with other AS-related pathologies such as Psoriasis and Behcet’s disease." (PMID 38892265, 2024). "Rs27524-G (CAST/ERAP1 locus) was associated with “ankylosing spondylitis” (OR = 0.84, p = 5.4 × 10−7), “iridocyclitis” (OR = 0.88, p = 6.9 × 10−8) and “psoriasis” (OR = 0.85, p = 1.6 × 10−6)." (PMID 39006426, 2024). "ERAP1′s enzymatic activity can impact the risk of these diseases: when increased, the risk for ankylosing spondylitis and psoriasis is elevated, whereas when it is reduced, the risk decreases for Birdshot chorioretinopathy (BSCR) and Behçet’s disease." (PMID 38534723, 2024). "A study showed that there is an interaction effect between HLA-C and ERAP1 in psoriasis, and ERAP1 variants influence psoriasis susceptibility only in individuals carrying the HLA-C risk allele." (PMID 39156563, 2024). "ERAP1/2 polymorphisms are strongly associated with HLA-I-related conditions like BD, psoriasis, AS, and birdshot chorioretinopathy." (PMID 38003572, 2023). "GWAS have unveiled non-additive gene-to-gene interactions between the HLA-class I risk alleles and specific variations of the endoplasmic reticulum aminopeptidase 1 (ERAP1), which can be linked with psoriasis risk." (PMID 37628670, 2023). "Epistatic effects between ERAP1 and AI-risk alleles have been observed, particularly with HLA-C∗06:02 in psoriasis, and suggest this risk interaction is tied to an increased likelihood of specific autoantigens making it to the cell surface." (PMID 37339630, 2023). "Multifactor dimensionality reduction (MDR) analysis was performed to identify the interaction between variants significantly associated with psoriasis in the validation cohort and ERAP1 variants." (PMID 36425068, 2022). "In summary, we screened for interactions between genes that affect psoriasis susceptibility and found that the most significant interaction was between the rs27044 polymorphism of ERAP1 and the rs7590692 polymorphism of IFIH1." (PMID 36425068, 2022). "In this study, we detected interactions of ERAP1 with other psoriasis susceptibility genes in the Han Chinese population." (PMID 36425068, 2022). "ERAP1 is more likely to be present in individuals carrying the HLA-C susceptibility allele, with the first and most important psoriasis susceptibility gene identified." (PMID 36425068, 2022). "This is of particular interest given the known interaction between HLA-B27 and ERAP1 variants in AS, and between HLA-Cw6 and ERAP1 variants in psoriasis." (PMID 35379982, 2022). "In a meta-analysis of nine case-control studies, the rs27044 polymorphism of ERAP1 was associated significantly with psoriasis." (PMID 36425068, 2022). "Another study showed an association of the ERAP1 rs27044 C/rs30187 T haplotype with a lower risk of extraspinal disease, defined as one of the following: peripheral arthritis, psoriasis, uveitis, and IBD." (PMID 35629038, 2022). "They generated ERAP1 knockout melanoma cell line and revealed that epistasis between HLA-C*06:02 and ERAP1 variants affects psoriasis." (PMID 35163260, 2022). "A recent study revealed that ERAP1 causes psoriasis by affecting HLA-C production via melanocyte autoantigens." (PMID 36425068, 2022).
psoriasis (continued). "Numerous genome-wide association studies (GWAS) have linked a common ERAP1 polymorphism at position 528 with susceptibility to inflammatory conditions of autoimmune etiology such as psoriasis, Behçet’s disease, and most strongly, with ankylosing spondylitis." (PMID 34489420, 2021). "The rs30187 (C/T) and rs27524 (G/A) polymorphisms of ERAP1 are associated with increased risk of psoriasis." (PMID 34395615, 2021). "Many polymorphisms in the ERAP1 gene have been shown to be associated with genetic susceptibility to psoriasis." (PMID 34395615, 2021). "One genome-wide association study confirmed that the polymorphism of ERAP1 rs26653 and rs27044 was associated with psoriasis in Chinese patients." (PMID 34395615, 2021). "This study is to investigate the relationship of endoplasmic reticulum aminopeptidase 1 (ERAP1) gene polymorphisms with psoriasis." (PMID 34395615, 2021). "In summary, ERAP1 polymorphism of rs30187 (C/T) and rs27524 (G/A) was associated with an increased risk of psoriasis." (PMID 34395615, 2021). "ERAP1 was identified by GWAS to be preferentially associated with early onset psoriasis among Chinese." (PMID 34395615, 2021). "Previous studies have shown that the ERAP1 gene is associated with other autoimmune disorders such as ankylosing spondylitis (AS) and psoriasis." (PMID 32023277, 2020). "ERAP1 is characterized by several common polymorphisms encoding variant amino acids related not only to BD, but also to ankylosing spondylitis (AS) and psoriasis." (PMID 31134098, 2019). "The major allele C (Arg528) instead reduces ERAP1 activity and, while protective for AS and psoriasis, is a risk factor for Behçet’s disease." (PMID 29991817, 2018). "Though further experiments are warranted, we suggest SNP rs27044 as a causal variant in the gene ERAP1 for psoriasis." (PMID 29715312, 2018). "More recent investigation into the classification of early onset psoriasis has confirmed the association of ERAP1 rs30187 and rs27044 (K528R and Q730E) only in HLA-C*06 positive individuals." (PMID 30054427, 2018). "Similar epistatic effects were also observed for psoriasis, such that individuals who carry variants in ERAP1 showed an increased risk only when they also carried an HLA-C risk allele." (PMID 28449694, 2017). "Endoplasmic reticulum aminopeptidase 1 (ERAP1) is another well-known gene associated with the genetic risk locus for psoriasis." (PMID 29232931, 2017). "Genetic variants within ERAP1 interact with HLA-Cw6 (genetic epistasis), such that ERAP1 risk alleles are only associated with psoriasis susceptibility in individuals harbouring HLA-Cw6." (PMID 26573299, 2016). "PTPN2 was associated with Crohn's disease and type I diabetes; ERAP1 was associated with psoriasis and multiple sclerosis." (PMID 25369137, 2014). "Interaction analysis successes include associating HLA-C interaction with ERAP1 with susceptibility for psoriasis, and HLA-B27 interaction with ERAP1 with susceptibility for ankylosing spondylitis." (PMID 24376627, 2013). "In a Chinese population, another SNP in ERAP1 (rs151823) was associated with early-onset psoriasis (less than 40 years) (GWAS, 8312 cases and 12919 controls)." (PMID 24069534, 2013). "Both studied revealed that ERAP1 influences psoriasis susceptibility only in individuals carrying the HLA-C risk allele." (PMID 22942706, 2012). "A role for peptide processing influencing psoriasis risk has been previously identified for the gene ERAP1, an amino peptidase which regulates the quality of peptides bound to MHC class I molecules through trimming the peptide N terminus." (PMID 22577363, 2012). "Two other recent GWAS identified ERAP1 as a new psoriasis susceptibility locus and evidence of an interaction between HLA-C*06:02 and ERAP1 was reported." (PMID 22942706, 2012).
psoriasis (continued). "A European study showed that rs27524A at the ERAP1 variant was associated with psoriasis (p = 0.019, OR = 1.34), especially in pediatric patients, which could be used as an independent risk factor (p = 0.042, OR = 1.43)." (PMID 39570751, 2024). "A gene called endoplasmic reticulum aminopeptidase 1 (ERAP1) has been associated with psoriasis." (PMID 39188726, 2024). "Finally, NGS analysis revealed that all patients carried several allelic variants in psoriasis susceptibility genes, such as HLA-C, ERAP1 and other genes of the major psoriasis susceptibility PSORS1 locus." (PMID 38495872, 2024). "Association of 18 ERAP1 variants with psoriasis in screening and validated stage." (PMID 39570751, 2024). "Moreover, we identified an association between Streptococcus abundance and psoriasis severity in patients with genetic variants related to IL-22, ERAP1, NOS2, and ILF3." (PMID 38898675, 2024). "This gene plays a role in peptide trimming for MHC class I presentation, and variations in ERAP1 may affect the immune response to self or foreign antigens, which might be associated with the pathogenesis of psoriasis." (PMID 39188726, 2024). "In primary screening stage, 13 genetic variants of ERAP1 showed an association with psoriasis." (PMID 39570751, 2024). "These associations imply that psoriasis could be caused by a T-cell initiated response to an autoantigen that is preferentially exhibited on HLA-C*0602 and processed by specific ERAP1 allele transcripts." (PMID 37628670, 2023). "Notably, an ERAP1 risk haplotype for psoriasis, including the same variants analysed in this study, has been proven to efficiently generate a melanocyte-derived autoantigen with a parallel increase of the predisposing HLA-C*06:02 molecules." (PMID 37686141, 2023). "AS belongs to the so-called “MHC-I-opathies”, together with the psoriasis, Behçet’s disease, birdshot uveitis and acute anterior uveitis for which GWAS have highlighted the association to ERAP1 and, sometimes, ERAP2, apart from the involvement of a key specific HLA-class I gene." (PMID 37686141, 2023). "Several other ERAP1 missense variants have been associated with inflammatory diseases, including rs30187 (K528R) with ankylosing spondylitis (AS; p = 4 × 10−45;73) and rs27044 (Q730E) with psoriasis (p = 8 × 10−21;74)." (PMID 36465279, 2022). "As ERAP1 has been recognized as a psoriasis susceptibility gene and plays a critical role in antigen presentation, we performed this study to identify interactions between ERAP1 and other psoriasis susceptibility gene variants." (PMID 36425068, 2022). "Interestingly, rs26653 in ERAP1 has been associated with several autoimmune diseases including psoriasis, ankylosing spondylitis and inflammatory bowel disease." (PMID 34149699, 2021). "ERAP1 haplotype is predisposing to psoriasis in East Asians." (PMID 34395615, 2021). "Two studies reported that rs151823 gene polymorphisms of ERAP1 may be also involved in the pathogenesis of psoriasis and treatment response of biologic therapies to psoriasis." (PMID 34395615, 2021). "Three studies reported rs27044 polymorphisms in the ERAP1 gene and psoriasis susceptibility." (PMID 34395615, 2021). "Our findings may provide a more comprehensive evaluation on the association of ERAP1 polymorphisms with psoriasis susceptibility." (PMID 34395615, 2021). "rs27524 polymorphism of ERAP1 is closely related to the susceptibility of psoriasis in Caucasians." (PMID 34395615, 2021). "The results of this study may provide a more comprehensive evaluation of the relationship between ERAP1 polymorphism and psoriasis susceptibility." (PMID 34395615, 2021). "However, due to the lack of antigen‐specific CD8+ T‐cell responses in HS patients, the link between the presence of SNPs in the HLA‐C region/ERAP1 gene and susceptibility to paradoxical psoriasis is apparently missing." (PMID 31577850, 2020).
psoriasis (continued). "Homozygosity of ERAP1 polymorphisms is proposed to be correlated with a lower risk of AS and psoriasis, whereas it might be associated with a higher risk of developing BD." (PMID 32023277, 2020). "Since the risk allele of rs2910686 (C) was the same as in AS this result suggests that, like in AS, ERAP2 expression may predispose to psoriasis, although the effect may often be masked by ERAP1." (PMID 30425713, 2018). "Association of ERAP1 with AS is restricted to individuals bearing the HLA-B risk factor for this disease, HLA-B27, whereas in psoriasis the relationship between ERAP1 and HLA-C remains unclear." (PMID 25019531, 2014). "Likewise, in psoriasis, ERAP1 variants rs30187 (K528R) and rs2287987 (M349V) contribute to inappropriate inflammatory responses through altered interactions with the HLA-C*06:02 molecule, a known psoriasis risk allele." (PMID 40226591, 2025). "Therefore, ERAP1 SNPs have been correlated with HLA-associated diseases like ankylosing spondylitis (AS), psoriasis, type 1 diabetes (T1D), inflammatory bowel disease, Behçet’s disease, cervical cancer, and hypertension, suggesting that ERAP1 polymorphisms can exert diverse effects." (PMID 39906739, 2024). "Polymorphisms in the ERAP1 gene may affect susceptibility to psoriasis." (PMID 34395615, 2021). "Therefore, the polymorphism of ERAP1 rs27524, rs30187, rs26653, and rs27044 may play significant roles in patients with psoriasis." (PMID 34395615, 2021). "Concerning miRNAs, it has been identified that hsa-miR-19a-3p has great potential to become a biomarker for psoriasis because it binds to the mRNA of seven genes (CAST, TSC1, SPATA2, ERAP1, TNIP1, ERBB3 and SDC4) thatare associated with psoriasis." (PMID 40725409, 2025). "The immunogenicity of melanocytes depends on IFN-γ, which is abundantly expressed in psoriasis lesions and upregulates HLA-C and ERAP1 that are both highly expressed by melanocytes in the basal epidermal layers of psoriasis lesions." (PMID 40243413, 2025). "The risk of psoriasis is increased by epistasis between HLA-C*06:02 and the enzymatically highly active ERAP1 haplotype Hap2, while the low-activity haplotype Hap10 protects against psoriasis." (PMID 41440022, 2025). "ERAP1 has been found to interact with HLA-C*06:02 in the context of Psoriasis in a similar manner as it does with HLA-B27 in Ankylosing Spondylitis." (PMID 38892265, 2024). "Concomitantly, oncological patients carried allelic variants in the ERAP1 gene, consistently with the presence CD8+ T-cell responses in psoriasis reactions to anti-PD-1." (PMID 38495872, 2024). "The interconnectedness between ERAP1, different HLA class I molecules, and the development of autoimmune diseases, including ankylosing spondylitis (AS), psoriasis (Ps), Birdshot chorioretinopathy (BSCR), and Behçet’s disease (BD)." (PMID 38534723, 2024). "Other than having a role in MHC class I antigen presentation, ERAP1 is involved in the activation of inflammasome pathways and production of cytokines and chemokines involved in psoriasis development (i.e., IL-6, TNF-α, and CCL2)." (PMID 38495872, 2024). "This was recently demonstrated for the homologous enzyme, ERAP1, in the case of Psoriasis, since reduced ERAP1 activity resulted in the reduced generation of an autoantigenic peptide that sustains cytotoxic T cell activity against melanocytes in patients." (PMID 35163832, 2022). "ERAP1 has been reported as being related to psoriasis in multiple populations, and our group has genotyped and replicated its polymorphisms." (PMID 36425068, 2022). "Gene–gene interaction (e.g., between HLA-C and ERAP1) in the psoriasis context has been reported in various populations." (PMID 36425068, 2022). "In contrast to BD, ERAP1 p.Asp725Gln acts protectively for AS under HLA-B*27 positivity and also for psoriasis under HLA-Cw6 positivity." (PMID 33912164, 2021).